PTTG1IP (PTTG1 interacting protein)
Description:
May facilitate PTTG1 nuclear translocation.
Synonyms: PBF; C21orf1; C21orf3; PTTG1IP1
Tractability: Antibody: UniProt predicts a signal peptide or a membrane-spanning region. PROTAC: ubiquitination databases record sites on it; its protein half-life has been measured.
Gene: Protein-coding gene on chromosome 21 (44,849,585 to 44,873,903, reverse strand). Ensembl gene ENSG00000183255.
Subcellular location: Membrane; Cytoplasm; Nucleus
Subcellular location (Human Protein Atlas): Nucleoplasm
Gene Ontology:
Molecular function: protein binding
Biological process: positive regulation of protein ubiquitination; protein import into nucleus
Cellular component: cytoplasm; extracellular exosome; membrane; nucleoplasm; nucleus
Genetic constraint (gnomAD): Loss-of-function variants: 15 observed, 22.88 expected, observed/expected ratio (o/e) 0.66, 90% interval 0.44 to 1.01. The upper end of that interval is the gene's LOEUF score, 1.01, which puts it in group 4 of 6, group 1 being the genes least tolerant of losing a copy. Missense variants: 239 observed, 225.58 expected, observed/expected ratio (o/e) 1.06, 90% interval 0.95 to 1.18. Synonymous variants: 89 observed, 84.6 expected, observed/expected ratio (o/e) 1.05, 90% interval 0.88 to 1.25.
Homologues: Orthologues: chimpanzee PTTG1IP (99% identical), macaque PTTG1IP (97% identical), dog PTTG1IP (82% identical), guinea pig PTTG1IP (76% identical), rat Pttg1ip (73% identical), mouse Pttg1ip (71% identical), pig PTTG1IP (69% identical), tropical clawed frog pttg1ip (56% identical). Paralogues in human: PTTG1IP2 (18% identical).
Diseases named in the same sentence as PTTG1IP in open-access papers:
PTTG1IP is named in the same sentence as 24 diseases in open-access papers, as found by Europe PMC text mining. Sharing a sentence is not in itself a finding about the gene and the disease. The quoted sentences say what the papers report.
thyroid cancer (6 papers, 2017 to 2025). "Pituitary tumor-transforming gene-binding factor (PBF/PTTG1IP) is upregulated in thyroid cancer and associated with poorer disease outcomes." (PMID 40748136, 2025). "The overexpression of PTTG1IP was associated with poor prognosis in epithelial ovarian cancer, thyroid cancer and head and neck squamous cell carcinoma." (PMID 39744132, 2024). "Previously, PTTG1IP-overexpression has been shown to repress the effect of radioiodide treatment in thyroid carcinoma." (PMID 29078751, 2017). "More recently, Smith and co-workers have, however, suggested that radioiodide uptake in thyroid cancer cells could be increased and, thus, efficacy of the treatment could be improved by targeting PTTG1IP expression via the modulation of phosphorylation." (PMID 29078751, 2017). "The expression of PTTG1IP has been reported in other malignant cancers including, CRC breast and thyroid cancers supporting its role as an oncogene." (PMID 37869015, 2023).
breast carcinoma (4 papers, 2017 to 2025). "In univariate analysis involving all breast cancer subtypes, PTTG1IP-negativity predicted a 1.5-fold risk for breast cancer death (p = 0.002, CI 0.9-2.7)." (PMID 29078751, 2017). "PTTG1IP-negativity alone and in combination with high securin immunoexpression indicates a high risk of breast cancer death, resulting in up to 14-year survival difference in our material." (PMID 29078751, 2017). "In contrast to previous literature, in our material comprising all breast carcinoma subtypes and up to 22-year follow-up, it was PTTG1IP-negativity that was associated with a 1.5-fold risk of breast cancer death." (PMID 29078751, 2017). "In breast carcinoma, an association between ER and PTTG1IP has been reported." (PMID 29078751, 2017). "Multivariate analysis was performed for PTTG1IP and securin, and the established prognosticators of breast cancer among all subtypes of breast carcinomas (n = 401)." (PMID 29078751, 2017). "The main part of our results supports the previous literature on PTTG1IP overexpression in breast carcinoma." (PMID 29078751, 2017). "In the present paper, we report on the expression pattern of PTTG1IP in 497 breast carcinomas, with up to 22 years of follow-up." (PMID 29078751, 2017). "In prognostic analyses, the breast cancer cases were analysed as divided into two categories (PTTG1IP 0 vs. 1+ − 3+ and securin <10% vs. ≥10% of cancer cells)." (PMID 29078751, 2017). "Among breast carcinomas of all subtypes (n = 401) PTTG1IP-immunopositivity was seen in 74.3% of the cases." (PMID 29078751, 2017). "A particularly convincing survival difference was observed for patients of all breast cancer subtypes between the most favourable (high PTTG1IP and low securin) and the most unfavourable (low PTTG1IP and high securin) outcome of the disease." (PMID 29078751, 2017). "A total of 497 breast carcinoma patients with up to 22-year follow-up were analysed for PTTG1IP and securin immunoexpression." (PMID 29078751, 2017). "In the present paper, we report on the expression patterns and prognostic value of PTTG1IP-immunoexpression in a total of 497 human breast carcinomas, including 96 cases of the triple-negative subtype." (PMID 29078751, 2017). "We have previously presented that the lack of PTTG1IP in breast cancer cells is associated with cytoplasmic localization of securin and that this protein expression profile was overrepresented in the triple-negative breast cancers (TNBC)." (PMID 29078751, 2017). "Interestingly, similar effect of regulation of PTTG1IP expression by phosphorylation has been observed in breast cancer cells." (PMID 29078751, 2017). "PTTG1IP overexpression has been previously observed in malignant disease, e.g. in breast carcinoma." (PMID 29078751, 2017). "Also, exposing breast cancer cell cultures to oestrogen has been shown to up-regulate PTTG1IP expression." (PMID 29078751, 2017). "We have demonstrated that the lack of PTTG1IP expression alone and in combination with high and cytoplasmic securin expression is associated with an increased risk of breast cancer death." (PMID 29078751, 2017). "In our material, negative PTTG1IP immunoexpression predicted a 1.5-fold risk of breast cancer death (p = 0.02)." (PMID 29078751, 2017). "As analysed in a material comprising of all breast cancer subtypes (n = 401), breast carcinomas lacking PTTG1IP immunoexpression and particularly the lack of PTTG1IP expression in combination with high securin expression were associated with an increased risk of breast cancer death." (PMID 29078751, 2017). "Among them, observations from breast cancer and colorectal carcinoma cell cultures have indicated that the overexpression of PTTG1IP increases cell invasion independent of increased proliferation." (PMID 29078751, 2017). "However, the prognostic value of PTTG1IP in breast carcinoma patients has not previously been revealed." (PMID 29078751, 2017).
bladder cancer (2 papers, 2023 to 2024). "SE-LINC00162 inhibits the transcription of PTTG1IP activated by THRAP3, thereby reducing the expression of PTTG1IP and promoting the proliferation of bladder cancer cells." (PMID 37501079, 2023). "Since PTTG1IP inhibits cell proliferation and promotes apoptosis, its downregulation due to LINC00162 overexpression and subsequent LINC00162–THRAP3 interaction promotes bladder cancer." (PMID 38542080, 2024). "Moreover, LINC00162, transcribed from the SE region in bladder cancer, interacts with THRAP3, thereby disrupting THRAP3’s ability to positively regulate PTTG1IP expression." (PMID 38542080, 2024).
glioma (2 papers, 2017 to 2024). A benign or malignant brain and spinal cord tumor that arises from glial cells (astrocytes, oligodendrocytes, ependymal cells). "Indeed, the dysregulation of miR-584-5p was found in both glial tumors and glioma cell lines where it acts as a tumor suppressor by targeting the PTTG1IP, a protein associated with tumor growth." (PMID 39000555, 2024). "In glioma cells, miRNA-584-expression has been shown to result in PTTG1IP down-regulation and suppression of tumour cell proliferation while down-regulation of miRNA-584 has been observed to up-regulate PTTG1IP and increase proliferation." (PMID 29078751, 2017).
anaplastic thyroid carcinoma (1 paper, 2017).
asthma (1 paper, 2018). "PTTG1IP and MAML3 (pituitary tumour-transforming 1 interacting protein (PTTG1IP) and rs345983 in Mastermind-like 3 (MAML3) are novel genomewide association genes for severity of hyperresponsiveness in adult asthma." (PMID 30498567, 2018).
Batten disease (1 paper, 2025). "A recent paper exploring the proteomic changes in microglia with another LSD, Batten disease caused by loss of CLN3, identify similar changes to those seen here, including increased TTYH3, PTTG1IP, LAMTOR3, PSAP, STARD3NL, TSPAN7, TMEM192 and NPC1." (PMID 40608809, 2025).
colorectal carcinoma (1 paper, 2017). A malignant epithelial neoplasm that arises from the colon or rectum and invades through the muscularis mucosa into the submucosa. "Previously, PTTG1IP overexpression has been associated with a poor prognosis in thyroid and colorectal carcinomas." (PMID 29078751, 2017). "As uncontrolled sister chromatid separation is one of the hallmarks of malignant progression, it is expectable that PTTG1IP overexpression has previously been observed in malignancy, eg. in thyroid, breast and colorectal carcinoma." (PMID 29078751, 2017).
endocrine cancers (1 paper, 2016). "The proto-oncogene PTTG1-binding factor (PBF/PTTG1IP) is overexpressed in multiple endocrine cancers and circumstantially associated with tumor aggressiveness." (PMID 27603901, 2016).
folate deficiency (1 paper, 2017). A nutritional condition produced by a deficiency of FOLIC ACID in the diet. "In addition, another outcome in our study that interested us was that, even in folate deficiency, the promoter CpG islands of some genes, such as CXADR, PWP2 and PTTG1IP, still presented a state of hypermethylation." (PMID 28881655, 2017).
hepatocellular carcinoma (1 paper, 2017). A malignant tumor that arises from hepatocytes. "Also, hepatitis virus B has been shown to induce miRNA-122 down-regulation leading to overexpression of PTTG1IP, and both an increase in cell proliferation and invasion in hepatocellular carcinoma cell lines." (PMID 29078751, 2017).
pituitary adenoma (1 paper, 2023). "miR-124 suppressed the migration and invasion of pituitary adenoma cells by targeting FSCN1, pituitary tumor-transforming gene 1 protein-interacting protein (PTTG1IP), and Ezrin (EZR)." (PMID 37508353, 2023).
thyroid (1 paper, 2017). "One such statistical approach – the Driver Oncogene and Tumor Suppressor Finder – predicted that the proto-oncogene PBF/PTTG1IP may be one of 12 genes driving thyroid carcinogenesis in 326 tumour samples from TCGA." (PMID 28676500, 2017).
triple-negative breast carcinoma (1 paper, 2017). An invasive breast carcinoma which is negative for expression of estrogen receptor (ER), progesterone receptor (PR), and human epidermal growth factor receptor 2 (HER2). "This PTTG1IP negative subgroup comprised the majority (78%) of triple-negative breast carcinomas where negative PTTG1IP expression was combined with high securin expression located in the cytoplasm of the cancer cells." (PMID 29078751, 2017).
tumor (14 papers, 2015 to 2025). "It was also highlighted that the overexpression of PTTG1IP in malignant tumours are the main driving force for tumour progression whilst genetic mutations are likely to establish minimal effects on PTTG1IP function." (PMID 37869015, 2023). "Background and Aims: The proto-oncogene pituitary tumor-transforming gene binding factor (PBF/PTTG1IP) is overexpressed in multiple tumours, including thyroid cancer, and is associated with tumour progression." (PMID 37434225, 2023). "Background and Aims: The proto-oncogene pituitary tumour transforming gene binding factor (PTTG1IP/PBF) is overexpressed in multiple tumours, including thyroid cancer, and is associated with tumour progression." (PMID 35869534, 2022). "In silico analysis revealed significant upregulation of PTTG1IP protein expression in the CRC tumour subgroup with a mean expression of 0.00 compared to their corresponding normal tissue subgroup with a mean expression of -0.554 (p<0.05)." (PMID 37869015, 2023). "Proteomics data outlined higher levels of PTTG1IP expression in COAD tumours with significant downregulation in the SHG-8 treated conditions confirming sequencing analysis." (PMID 37869015, 2023). "The pathways leading to PTTG1IP regulation are still unsettled but miRNA-584, a known tumour suppressor, has been suggested among them." (PMID 29078751, 2017). "PTTG1IP can promote tumor growth and invasion ability, and its high expression is independently associated with poor prognosis and lower disease-specific survival." (PMID 26571024, 2015). "In vitro experiments demonstrated that EFNB2, PTTG1IP, and TNFRSF11A were upregulated in dormant tumor cells, which also contributed greatly to the diagnosis of LUAD." (PMID 39273449, 2024). "In vivo Cre delivery was demonstrated using EVs expressing PTTG1IP-intein-Cre and VSVG in mice harboring B16 reporter cell tumor xenografts." (PMID 39712388, 2024). "We previously characterised PBF (pituitary tumor-transforming gene 1-binding factor; also known as PTTG1IP or c21orf3) as a proto-oncogene based on the transformation potential of PBF in vitro and its ability to induce tumours in xenograft models." (PMID 28676500, 2017). "CAFs-Exo was found to be involved in tumor immune regulation through hsa-miR-139-5p, ACTR2 and EIF6, while PIGR, CD81, UACA and PTTG1IP may be potentially effective targets for the treatment of OSCC in the future." (PMID 37365497, 2023).
cancer (5 papers, 2017 to 2024). A tumor composed of atypical neoplastic, often pleomorphic cells that invade other tissues. "Although some mutations in the PTTG1IP gene can be found listed in databases such as the COSMIC (Catalogue of Somatic Mutations in Cancer), the clinical relevance of these mutations is still unclear." (PMID 29078751, 2017). "In previous literature, modulation of PTTG1IP expression has already been investigated and appears a promising pathway for development of future cancer treatments." (PMID 29078751, 2017). "Evaluating the extent of PTTG1IP-positivity revealed that 17% of carcinomas showed weak staining (<10% of cancer cells, score 1+), 41% moderate staining (10-50% of cancer cells, score 2+) and 15% diffuse staining (≥50% of cancer cells, score 3+)." (PMID 29078751, 2017). "There are 4 genes (UACA, PTTG1IP, PIGR, CD81) of this GO term may interacted with ACTR2, EIF6 and hsa-miR-139-5p at the same time, and they play an important role in cancer associated pathway: apoptotic process (UACA, PTTG1IP) and immunity (PIGR, CD81)." (PMID 37365497, 2023). "Total PTTG1IP-negativity (score 0) was observed in 26% of carcinomas." (PMID 29078751, 2017). "Further quartile estimations of survival curves indicated that the majority (75%) of the patients with PTTG1IP-positive carcinoma survived 11.4 years while the majority of patients a carcinoma lacking PTTG1IP expression were alive only 6.4 years after diagnosis." (PMID 29078751, 2017). "Although, there are conflicting reports for the expression of PTTG1IP in malignant tumours, further assessment of the mechanistic action of the miR-6715b-3p/PTTG1IP axis in correlation with the Siglec-15/Sia axis could shed some light on CRC progression and maybe a promising approach for treatment." (PMID 37869015, 2023). "This statistical association could also be verified morphologically in IF-double-staining where cancer cells exhibiting PTTG1IP-positivity showed nuclear securin expression while, in absence of PTTG1IP, securin expression showed a shift towards cytoplasmic subcellular location." (PMID 29078751, 2017).
PTTG1IP also shares sentences with these, for which no sentence is quoted: breast tumors (1 paper); colorectal tumors (1); head and neck squamous cell carcinoma (1); keratitis (1); lung carcinoma (1); papillary thyroid carcinomas (1); pituitary tumor (1); viral infection (1).